MBNL3 (muscleblind like splicing regulator 3)
Description:
Mediates pre-mRNA alternative splicing regulation. Acts either as activator or repressor of splicing on specific pre-mRNA targets. Inhibits cardiac troponin-T (TNNT2) pre-mRNA exon inclusion but induces insulin receptor (IR) pre-mRNA exon inclusion in muscle. Antagonizes the alternative splicing activity pattern of CELF proteins. May play a role in myotonic dystrophy pathophysiology (DM). Could inhibit terminal muscle differentiation, acting at approximately the time of myogenin induction.
Synonyms: CHCR; MBLX39; MBXL; FLJ11316; MBLX
Tractability: PROTAC: ubiquitination databases record sites on it.
Gene: Protein-coding gene on chromosome X (132,369,320 to 132,489,978, reverse strand). Ensembl gene ENSG00000076770.
Subcellular location: Nucleus; Cytoplasm
Subcellular location (Human Protein Atlas): Nucleoplasm; Cytosol
Gene Ontology:
Molecular function: protein binding; RNA binding; metal ion binding
Biological process: regulation of RNA splicing
Cellular component: cytosol; nucleoplasm; cytoplasm; nucleus
Homologues: Orthologues: chimpanzee MBNL3 (99% identical), macaque MBNL3 (98% identical), pig MBNL3 (92% identical), rabbit MBNL3 (84% identical), dog MBNL3 (84% identical), mouse Mbnl3 (81% identical), guinea pig MBNL3 (80% identical), tropical clawed frog mbnl3 (75% identical), rat Mbnl3 (71% identical), zebrafish mbnl3 (70% identical), Drosophila melanogaster mbl (45% identical), Caenorhabditis elegans mbl-1 (24% identical). Paralogues in human: MBNL1 (68% identical), MBNL2 (63% identical), ZC3H10 (20% identical).
Diseases named in the same sentence as MBNL3 in open-access papers:
MBNL3 is named in the same sentence as 21 diseases in open-access papers, as found by Europe PMC text mining. Sharing a sentence is not in itself a finding about the gene and the disease. The quoted sentences say what the papers report.
hepatocellular carcinoma (6 papers, 2019 to 2024). A malignant tumor that arises from hepatocytes. "The lncRNA FIRRE expression was elevated in hepatocellular carcinoma and associated with MBNL3 for promoting the splicing activity of PXN or PFKFB4 for glycolysis." (PMID 38556083, 2024). "The muscleblind-like-3 (MBNL3) splicing factor promotes hepatocellular carcinoma (HCC) by increasing paxillin (PXN) expression through the alternative splicing of lncRNA-PXN-AS1." (PMID 31576812, 2019). "Muscleblind-like-3 (MBNL3) is an oncofetal splicing factor expressed in hepatocellular carcinoma (HCC) tissues." (PMID 31717266, 2019). "Paxillin antisense RNA 1 (PXN-AS1), a lncRNA overlapping PXN mRNA, was identified after discovering alternative splicing events on a transcriptome sequencing analysis of a hepatocellular carcinoma (HCC) cell line with stable deletion of Muscleblind-like-3 (MBNL3), an oncofetal splicing factor." (PMID 33466464, 2021). "Muscleblind-like-3 (MBNL3), a oncofetal splicing factor, was high expressed in hepatocellular carcinoma (HCC) compared with normal liver tissues, and modulated the alternative splicing of PXN antisense transcript 1 (lncRNA-PXN-AS1)." (PMID 33531995, 2021). "For example, MBNL3 regulates the AS of the lncRNA PXN-AS1 and promotes the inclusion of exon 4 to upregulate PXN in hepatocellular cancer." (PMID 37303939, 2021).
myotonic dystrophy (2 papers, 2013 to 2016). An inherited progressive disorder affecting the muscles. "In human, MBNL proteins, encoded by three members MBNL1, MBNL2 and MBNL3, are key splicing factors in the neuromuscular disease myotonic dystrophy (DM)." (PMID 23685613, 2013).
amyotrophic lateral sclerosis (1 paper, 2025). Amyotrophic lateral sclerosis (ALS) is a neurodegenerative disease characterized by progressive muscular paralysis reflecting degeneration of motor neurons in the primary motor cortex, corticospinal tracts, brainstem and spinal cord. "MBNL3, an RNA-binding protein involved in RNA metabolism and splicing, has been linked to diseases such as autism and amyotrophic lateral sclerosis." (PMID 40539039, 2025).
cataract (1 paper, 2016). Partial or complete opacity of the crystalline lens of one or both eyes that decreases visual acuity and eventually results in blindness. "This is in contrast to Mbnl3+/+ animals, where only one of eight lenses showed grade 1 subcapsular cataracts at 12 months of age." (PMID 27484195, 2016).
gastric adenocarcinoma (1 paper, 2024). "MBNL3 was revealed to act as a target of miR-302e to facilitate cell proliferation, invasion, and angiogenesis of gastric adenocarcinoma through the AKT/VEGFA pathway." (PMID 38955795, 2024). "In conclusion, MBNL3 acted as a target of miR-302e to facilitate cell proliferation, invasion, and angiogenesis of gastric adenocarcinoma through the AKT/VEGFA pathway." (PMID 38955795, 2024). "Our results revealed that MBNL3 exhibited higher expression, and MBNL3 acted as a target of miR-302e to facilitate cell proliferation, invasion, and angiogenesis of gastric adenocarcinoma through the AKT/VEGFA pathway." (PMID 38955795, 2024).
leukemia (1 paper, 2020). A malignant (clonal) hematologic disorder, involving hematopoietic stem cells and characterized by the presence of primitive or atypical myeloid or lymphoid cells in the bone marrow and the blood. "In both Mbnl1+/+ and Mbnl1−/− states Mbnl2 and Mbnl3 are stably expressed in mouse leukemia cells, however neither analogue was meaningfully expressed in the human leukemia lines assayed." (PMID 32398749, 2020).
lung carcinoma (1 paper, 2019). "Remarkably, the list of genes included PXN-AS1, which was reported to interact with the nuclear-localized splicing factor MBNL3 to promote liver and lung cancer progression." (PMID 31781161, 2019).
Myotonia (1 paper, 2018). An involuntary and painless delay in the relaxation of skeletal muscle following contraction or electrical stimulation. "Dual depletion of Mbnl1 and Mbnl3 also enhanced myotonia, muscle weakness and myopathy in skeletal muscle." (PMID 30050493, 2018). "Instead, enhanced myotonia was the result of the synergy between Clcn1 missplicing caused by Mbnl1 deletion alone, and defective CLCN1 translation, caused by combined inactivation of MBNL1 and MBNL3 proteins." (PMID 30050493, 2018).
ovarian carcinoma (1 paper, 2023). A malignant neoplasm originating from the surface ovarian epithelium. "MBNL3 participates in paclitaxel resistance in ovarian cancer." (PMID 38155938, 2023).
cancer (6 papers, 2020 to 2025). A tumor composed of atypical neoplastic, often pleomorphic cells that invade other tissues. "Recent reports revealed that MBNL3 expression is dysregulated in diversified cancers, thereby affecting tumor growth and development." (PMID 38955795, 2024). "Muscleblind-like 3 (MBNL3) was found to be a pivotal participator in aggravating this cancer’s progression." (PMID 38955795, 2024). "To find potentially approved drugs that target MECOM, RCN2, and MBNL3, we screened the herb database for related small molecules with anti-cancer effects." (PMID 36171401, 2022). "By regulating AS, splicing factors, such as PTBP1 and MBNL3, can function as oncogenes or pseudo‐oncogenes and promote cancer progression." (PMID 32939931, 2020). "Genes such as PYGM, BMF, MBNL3, DENND6A, REEP5, KLF6 and ITM2C are potentially regulated by circYPEL2 and involved in cancer-specific pathways, which are needed to be validated in further studies." (PMID 35052380, 2021). "Our findings that MBNL3 and KANSL2 regulate PDAC cell invasion add to the growing knowledge that MBNL3 and KANSL2 play important roles in cancer metastasis, and warrant further investigation to define the underlining mechanisms in order to validate them as potential therapeutic targets for PDAC." (PMID 32001790, 2020).
tumor (5 papers, 2022 to 2025). "To better elucidate the impact of MECOM, RCN2, and MBNL3 on the tumor microenvironment and immunotherapy, we conducted an immune infiltration analysis." (PMID 36171401, 2022). "Similarly, lncRNA SBF2 antisense RNA 1 (SBF2-AS1) enhances radioresistance through the miR-302a/MBNL3 axis, where MBNL3 knockdown sensitizes tumor cells to DNA damage." (PMID 41409273, 2025). "Through in vivo assay, it was proved that inhibition of MBNL3 slowed tumor growth in vivo." (PMID 38955795, 2024). "The expression of MBNL3 was positively correlated with the degree of neutrophil infiltration, suggesting that MBNL3 may affect tumor occurrence by reducing neutrophil infiltration." (PMID 36171401, 2022). "Genes TBX3, CASP3, MBNL3, and SEPT2 were enriched in tumor pathways and their AS level changes were confirmed by RT-qPCR experiments." (PMID 38155938, 2023).
MBNL3 also shares sentences with these, for which no sentence is quoted: pancreatic ductal adenocarcinoma (2 papers); prostate carcinoma (2); autism (1); cardiovascular diseases (1); colon cancer (1); colorectal cancer (1); intrauterine growth restriction (1); neuromuscular disease (1); pancreatic cancer (1); psychiatric disease (1).